POMC (proopiomelanocortin)
Diseases named in the same sentence as POMC in open-access papers (continued):
Sharing a sentence is not in itself a finding about the gene and the disease.
Obesity (continued). "Moreover, mitochondrial ribosomal stress applied to POMC neurons induces MOTS-c in POMC neurons and nonautonomous activation of the UPRmt in adipose tissue, improving metabolism and increasing resistance to obesity in mice." (PMID 37109535, 2023). "At present, there is no curative option for POMC-mutant-driven obesity." (PMID 37152279, 2023). "Interestingly, Sirtuin 1 (SIRT1), a transcriptional target of TAp63, plays a sex-specific role in POMC neurons to prevent obesity in females but not in males, similar to effects of TAp63." (PMID 33826123, 2022). "It is well known that hypothalamic inflammation reduces the responsiveness of POMC and NPY neurons in the ARC to the physiological actions of leptin and insulin and alters the normal activity of the orexigenic and anorexigenic peptides, thereby promoting energy imbalance and obesity." (PMID 35683029, 2022). "In food-induced obesity, the whole-body energy homeostasis is disrupted, which may be related to abnormalities in hypothalamic neurons, e.g., NPY/agouti gene-related peptidergic neurons stimulating POMC/cocaine- and amphetamine-induced transcriptergic neurons." (PMID 34733235, 2021). "HFD results in a downregulation of Mfn2 expression, increased mitochondrial density, and decreased mitochondria–ER contacts in POMC neurons, illustrating that MFN2 is involved in metabolic alterations following diet-induced obesity and so may be involved in the central regulation of energy balance." (PMID 33240218, 2020). "Notably, however, the recovery of the POMC neuron number in our cilia mutants in adulthood neither rescued the reduced axonal fiber density nor prevented the development of obesity." (PMID 33188191, 2020). "The observed changes in the inhibitory synaptic activity suggested alterations in the synaptic input organization of POMC neurons but could not provide a simple explanation for the obesity phenotypes in POMC cilia mutants." (PMID 33188191, 2020). "Additionally, leptin inhibits NPY and activates POMC, creating a negative feedback loop that prevents obesity." (PMID 32987812, 2020). "Besides, it was first reported that proopiomelanocortin (POMC)–specific ablation of Mfn2 results in endoplasmic reticulum (ER) stress–induced leptin resistance and decreased energy expenditure for protection against obesity." (PMID 31551926, 2019). "Moreover, disruption of GABA release from a specific subset of non-AgRP non-POMC neurons of the arcuate nucleus of mice induced obesity through decreasing energy expenditure." (PMID 30406389, 2019). "Interestingly, diet-induced obesity/insulin resistance enhances NOP receptor-mediated activation of GIRK channels in POMC neurons from female but not male animals." (PMID 30755252, 2019). "Therefore, we propose that perturbations in glucose metabolism in obesity, may at least in part be due to TCPTP repressing the IR-dependent activation of POMC neurons and the overall melanocortin output response." (PMID 30230471, 2018). "Lack of autophagy in hypothalamic POMC neurons promotes obesity as well as metabolic dysfunction." (PMID 28913352, 2017). "Meanwhile, re-expression of POMC in this neuronal subpopulation in females corrected only food intake and insulin sensitivity but did neither increase physical activity, energy expenditure nor block the development of obesity." (PMID 27609221, 2016). "However, deletion of PI3K in POMC neurons does not appear to lead to widespread obesity and does not affect long term whole body weight regulation." (PMID 26578907, 2015). "Also, they showed that the lack of AMPK in POMC neurons led mice to obesity because of their suppressed metabolic rate and increased feeding." (PMID 25634597, 2015). "Still, leptin is suggested to exert anti-obesity effects by signaling through “long form” leptin receptors (ObR) abundantly present on both orexigenic neuropeptide Y (NPY)/agouti-related peptide (AgRP) neurons and anorexigenic pro-opiomelanocortin (POMC) neurons in the Arc." (PMID 23554574, 2013).
Obesity (continued). "And the female mice without SIRT1 in POMC neuron are more sensitive to diet-induced obesity." (PMID 21738790, 2011). "However, in ob/ob mice (who congenitally lack leptin, leading to obesity), leptin deficiency exaggerates the direct inhibitory effect of NPY neurones on POMC neurones in the arcuate nucleus, an effect independent of the actions of GABA." (PMID 17764572, 2007). "Similarly, no obesity development in mice with MC4R overexpression in PVHMC4R neurons may be due to compensatory changes in upstream POMC neurons." (PMID 37069175, 2023). "However, our study reveals that maternal obesity does not affect AgRP circuits during early postnatal life whereas it affects POMC axonal projections, suggesting that distinct mechanisms underlie the effects of maternal HFHS feeding on POMC neurons versus AgRP/NPY neurons." (PMID 32163401, 2020). "In this context, the identification of ARC neuromediators other than those released by the POMC/CART and NPY/AgRP/GABA neurons that could relay the catabolic message of leptin via the melanocortin system, appeared justified in our understanding of the pathophysiology of obesity." (PMID 28690493, 2017). "However, it should be noted that deletion of LepRs in POMC neurons, which may decrease neuronal firing frequency, resulted in only a mild obesity with no increase in food intake." (PMID 23734095, 2013). "HO patients retain the specific expression of POMC/LEPR/MC4R in the PVN, but there are currently no large-scale clinical studies on the treatment of obesity." (PMID 41601974, 2026). "Surprisingly, activation of XBP-1s in hypothalamic pro-opiomelanocortin (POMC) neurons of mice leads to cell non-autonomous induction of the UPRER in the liver, which protects the mice from diet-induced obesity and helps maintain metabolic homeostasis." (PMID 38500817, 2024). "Our results that chronic activation in both POMC and MC4R neurons does not affect body weight reduction or obesity prevention are somewhat surprising." (PMID 37069175, 2023). "Congenital RPGRIP1L hypomorphism in POMC neurons leads to hyperphagic obesity and increased adiposity; however, deletion of RPGRIP1L in adult POMC neurons did not result in an obesity phenotype." (PMID 36568981, 2022). "Sel1LPOMC mice develop obesity accompanied by impaired leptin response in the POMC neurons, but the primary defect in the absence of ERAD appears to involve defective POMC processing in the ER." (PMID 29457782, 2018). "Although POMC is not abundantly expressed within the NTS, we report that POMC in this region is required for 5-HT2CR agonist obesity medications to acutely reduce food intake." (PMID 30146485, 2018). "Although specific knockout of SIRT1 in POMC neurons does not affect feeding behavior, mice lacking SIRT1 in POMC neurons demonstrate hypersensitivity to diet-induced obesity by reduced energy expenditure." (PMID 30416425, 2018). "The lack of pro-opiomelanocortin (POMC)-derived melanocortin peptides results in hypoadrenalism and severe obesity in both humans and rodents that is treatable with synthetic melanocortins." (PMID 30201275, 2018). "Mice lacking ROCK1 in either POMC or NPY/AgRP neurons, display impaired leptin sensitivity and obesity." (PMID 28270795, 2017). "Here, we showed that mice lacking IRE1α specifically in POMC neurons (PIKO) are lean and resistant to high-fat diet-induced obesity and obesity-related insulin resistance, liver steatosis and leptin resistance." (PMID 27558934, 2016).
Obesity (continued). "Correspondingly, it is ablation of ARC POMC, not NTS POMC neurons, which is required for the development of obesity, increased fat mass and glucose intolerance, with the former neurons being stimulated by leptin, while the latter are stimulated by cholecystokinin (CCK) and inhibited by opioids." (PMID 38019584, 2024). "Importantly, neither the inhibition of NPY nor the inhibition of POMC in OP mice were capable of modifying their phenotype, which reinforces the hypothesis that an early reduction of POMC following the introduction of a HFD is involved in the increased predisposition to obesity." (PMID 27373214, 2016). "However, when LEPR was in vivo abrogated in proopiomelanocortin (POMC) neurons of ARCs, which are well-known to foster fullness and satiety responses, mice developed mild obesity, hyperleptinaemia and glucose intolerance without changes in food consumption or EE." (PMID 34208585, 2021). "In ganglioside-depleted POMC neurons, neither PStat3 nor PIP3 formation is increased by peripheral leptin injections, strongly suggesting that defects in both pathways may contribute to partial failure of obesity prevention." (PMID 23554574, 2013). "Interestingly, selective elimination of LEPRb in the steroid factor 1 (SF1)-expressing neurons of the VMH also produced an obesity phenotype, with a cumulative effect in mice lacking LEPRb in both SF1 and POMC neurons, indicating that these may represent distinct parallel pathways." (PMID 23543912, 2013).
Cushing syndrome (607 papers, 1997 to 2026). Cushing's syndrome (CS) encompasses a group of hormonal disorders caused by prolonged and high exposure levels to glucocorticoids that can be of either endogenous (adrenal cortex production) or exogenous (iatrogenic) origin. "LC-TPIT primarily includes genes implicated in Cushing syndrome (e.g., POMC, EGFR), and LC-SF1 is enriched for components of the GnRH signaling pathway (e.g., LHB, FSHB)." (PMID 41253784, 2025). "In this report we describe the case of severe Cushing's syndrome caused by a metastatic pancreatic neuroendocrine tumor associated with the presence of high molecular weight ACTH-precursor molecules, possibly POMC, detected in the tumoral tissues." (PMID 32903471, 2020). "POMC plasma level was determined as a potential differential marker of ACTH-dependent Cushing’s syndrome." (PMID 36986097, 2023). "Such a steroidogenic role for POMC has already been suggested by cases of clinically overt Cushing’s syndrome revealing high plasma concentrations of POMC and (very) low plasma ACTH." (PMID 33593393, 2021). "This case emphasizes the relationship between ectopic ACTH-secreting Cushing's syndrome and importance of ACTH precursors quantification such as POMC." (PMID 32903471, 2020). "The overexpression of pro-opiomelanocortin (POMC) and the subsequent hypersecretion of adrenocorticotropic hormone (ACTH) are hallmark features of ACTH-secreting tumors, leading to the clinical manifestations of Cushing’s syndrome." (PMID 40002253, 2025). "To conclude, although we could not measure serum level of POMC, we were able to demonstrate its presence in two different tumor tissues (liver and pancreas) from a patient with an aggressive Cushing's syndrome." (PMID 32903471, 2020).
Adrenal insufficiency (438 papers, 2008 to 2026). Insufficient production of steroid hormones (primarily cortisol) by the adrenal glands. "Rather, impaired POMC processing in the pituitary induces adrenal insufficiency which increases susceptibility to endotoxemia due to lack of anti-inflammatory action of glucocorticoids." (PMID 39435302, 2024). "For example, proopiomelanocortin (POMC) deficiency is a monogenic obesity syndrome, associated with tall stature, fair skin and adrenal insufficiency, with severe and potentially fatal immune disruption." (PMID 37275420, 2023). "Adrenal insufficiency due to proopiomelanocortin (POMC) gene mutation was found in one infant, glycogen storage disease type 1 in one patient, glycogen storage disease type 3 in one patient, and Beckwith-Wiedemann syndrome in one patient." (PMID 36382321, 2022). "The patient with POMC mutation also showed typical features of the disease with dysmorphic features, adrenal insufficiency, and red hair." (PMID 36382321, 2022). "In primary adrenal insufficiency, there is a significant increase in POMC production as a response to decreased cortisol levels, leading to the release of αMSH and causing the subsequent hyperpigmentation." (PMID 38744309, 2024). "POMC was not included in this study based on the assumed adrenal insufficiency associated to pathogenic variants in this gene." (PMID 30926952, 2020).
pituitary adenomas (406 papers, 2005 to 2026). "In an in vitro experiment, proopiomelanocortin-derived peptide secretion from a pituitary adenoma causing NS was reduced by somatostatin-14 and somatostatin-28." (PMID 37332454, 2023). "Our findings on the role of UPS in POMC/ACTH turnover are of particular interest given the recent reports on gain-of-function mutations in the thiol protease deubiquitinase USP8 gene in patients with ACTH-secreting pituitary adenomas, i.e., Cushing’s disease." (PMID 29536250, 2018). "Forced overexpression of TSP‐1 suppressed proliferation, migration and invasion in pituitary adenoma cells and decreased POMC transcription and ACTH secretion." (PMID 31016850, 2019). "Taken together, these results indicate that BRAF V600E contribute to the pathogenesis of ACTH-secreting pituitary adenomas through increased phosphorylation of POMC transcription regulators including Nur77, c-jun, and c-fos." (PMID 30093687, 2018). "Ectopic ACTH tumours are characterised by an abnormal circulating ACTH precursor to ACTH ratio as compared to ACTH secreting pituitary adenoma due to a possible aberrant POMC processing." (PMID 26904316, 2016). "First, large pituitary adenomas may be less differentiated and less efficient at the processing of proopiomelanocortin to ACTH, resulting in the production of biologically less potent ACTH precursors and fragments that may cross-react in the ACTH assay." (PMID 35329884, 2022). "Consequently, sustained EGFR signaling in pituitary adenoma leads to enhanced promoter activity of the gene encoding proopiomelanocortin (POMC), the precursor of ACTH." (PMID 32344852, 2020). "Moreover, studies have shown that pituitary adenomas with mutated USP8 display an increased incidence of EGFR expression, EGFR protein abundance and the mRNA expression levels of POMC, indicating that EGFR plays an important role in adenomaigenesis." (PMID 31798535, 2019). "Interestingly, in this study pituitary adenoma formation in vivo was monitored by crossing conditional Rb knockout mice with transgenic mice that express luciferase under the control of the POMC promoter detecting tumor growth as early as 8 weeks of age." (PMID 25136513, 2014). "The classical presentation of Nelson's syndrome includes characteristic bronzing of the skin (due to proopiomelanocortin expression), frequent enlargement of the residual pituitary adenoma due to loss of negative feedback inhibition, and elevated serum ACTH levels (typically greater than 200 ng/L)." (PMID 23401686, 2013). "Given this premise, we decided to evaluate POMC expression as well as CRH-R1 and glucocorticoid receptor expression in ACTH-secreting pituitary adenomas and their response to CRH and dexamethasone in vitro." (PMID 27220856, 2017). "Indeed, EGFR is expressed in ACTH-secreting pituitary adenomas in both species, and its inhibition with the EGFR inhibitor gefitinib has been shown to reduce POMC expression, subsequent ACTH production, and corticotroph cell proliferation." (PMID 40943544, 2025). "Possible limitations of the study include a lack of understanding as to the mechanism by which deletion of one or both copies of the POMC gene results in the consistent, spontaneous development of aggressive, nonfunctioning pituitary adenomas." (PMID 32591776, 2020). "Furthermore, complete arrest of spontaneously developing, aggressive, nonfunctioning pituitary adenomas was observed in vivo in proopiomelanocortin KO mice, an effect not observed with pure SRIF or dopamine analogs, either alone or in combination." (PMID 30232095, 2018).
hypercortisolism (376 papers, 2006 to 2026). "Some cause elevated circulating adrenocorticotropic hormone (ACTH) levels, though manifestations of hypercortisolism are infrequently seen due to the incomplete processing of the proopiomelanocortin (POMC) peptide." (PMID 40565361, 2025). "EGFR is expressed in 75% of human corticotroph adenomas, and gefitinib treatment of human primary pituitary corticotroph tumor cultures reduced POMC mRNA and reversed features of hypercortisolemia." (PMID 34867776, 2021). "Whereas, overexpression of POMC has been found in SCA tumor tissues, the expression of PC1/3 was decreased; thus, POMC could not be broken down into enough ACTH to cause typical hypercortisolism." (PMID 33071973, 2020). "Progressive expression of POMC and ACTH by these cells then results in adrenocortical hyperplasia and hypercortisolism via activation of the cAMP/pKA pathway by the MC2R." (PMID 25941513, 2015). "Changes in posttranslational processing of the ACTH prohormone POMC may result in secretion of biologically active ACTH and development of endogenous hypercortisolism." (PMID 24455332, 2013).